EGFR (epidermal growth factor receptor)
Diseases named in the same sentence as EGFR in open-access papers (continued):
Sharing a sentence is not in itself a finding about the gene and the disease.
non-small cell lung carcinoma (continued). "Although EGFR-TKI treatment of NSCLC (non-small-cell lung cancer) patients often achieves profound initial responses, the efficacy is transient due to acquired resistance." (PMID 34203709, 2021). "Downregulating miR-365 in non-small-cell lung cancer cells was shown to upregulate the EGFR/PI3K/AKT axis through the pro-metastatic transcription factor homeobox protein Nkx-2.1 (NKX2-1)." (PMID 34064589, 2021). "Epidermal growth factor receptor (EGFR) 20 exon insertion is the second most common EGFR aberrations in non-small cell lung cancer (NSCLC)." (PMID 34398022, 2021). "This consequently upregulates EGFR and activates its downstream signaling pathways as well as stemness of non-small cell lung cancer (NSCLC)." (PMID 34712671, 2021). "ErbB receptors, especially ErbB2 and EGFR, are overexpressed in many cancers such as non-small-cell lung cancer, ovarian cancer, and breast cancer." (PMID 33763152, 2021). "An effective therapeutic target, for example, in RAS wild-type colorectal cancer and EGFR-mutated non-small-cell lung cancer (NSCLC), is aberrant activation of ERBB signaling pathways." (PMID 34768978, 2021). "Epidermal growth factor receptor (EGFR) kinase domain duplication (KDD) has been identified as an oncogenic driver in 0.05% to 0.14% of non-small cell lung cancer (NSCLC) patients." (PMID 34240806, 2021). "For LUAD, PTPRB is the only identified gene and is found to be mutually exclusive with EGFR, a well-known oncogene in non-small cell lung cancer." (PMID 34899838, 2021). "MET amplification plays an important role in the development of non-small-cell lung cancer (NSCLC) either de novo or in resistance to epidermal growth factor receptor tyrosine–kinase inhibitor (EGFR-TKI) settings." (PMID 34758872, 2021). "In non-small cell lung cancer (NSCLC), the EGFR tyrosine kinase (TK) domain mutations in cancer cells are strongly associated with a higher sensitivity to EGFR tyrosine kinase inhibitor (TKI)." (PMID 34439260, 2021). "EGFR exon 20 insertions are rare genetic alterations in non-small-cell lung cancers (NSCLCs) that are usually unresponsive to approved EGFR tyrosine kinase inhibitors (TKIs), but data is limited about this population." (PMID 34680280, 2021). "Dysfunctional and activating epidermal growth factor receptor (EGFR) is one of the major oncogenic drivers in non-small cell lung cancer (NSCLC)." (PMID 34885115, 2021). "ID1 is associated with resistance to the first generation of EGFR tyrosine kinase inhibitors (EGFR-TKIs) in non-small cell lung cancer (NSCLC)." (PMID 33992097, 2021). "While non-small-cell lung cancer (NSCLC) is highly heterogeneous, mutations in the epidermal growth factor receptor (EGFR) gene, leading to aberrant EGFR signaling, occur in up to 50% of Asian patients." (PMID 34253172, 2021). "EGFR mutant non-small cell lung cancers are resistant to EGFR tyrosine kinase inhibitor (EGFR-TKI), and BRAF fusion is one of the reasons for their resistance." (PMID 34368119, 2021). "Epidermal growth factor receptor-directed treatment of non-small-cell lung cancer represents a clinical setting where ctDNA already has entered the clinic." (PMID 33924696, 2021). "Data from non-small cell lung cancer (NSCLC) also imply a role of EGFR in resistance towards immune checkpoint inhibitor therapy." (PMID 33916908, 2021). "Among them, small-molecule TKIs for EGFR, including gefitinib, erlotinib, afatinib, osimertinib, and dacomitinib, have been initially approved to treat non-small cell lung cancer (NSCLC)." (PMID 34207383, 2021). "Our study focused on the mechanism of resistance acquisition to epidermal growth factor receptor tyrosine kinase inhibitors (EGFR-TKIs) in non-small cell lung cancers (NSCLCs)." (PMID 34271973, 2021). "Anti-EGFR therapies, such as gefitinib, erlotinib, and cetuximab, promote autophagy in non-small cell lung cancer as a survival mechanism and result in resistance to anti-EGFR therapy." (PMID 34829834, 2021).
non-small cell lung carcinoma (continued). "Non-small-cell lung cancer patients who responded to EGFR-tyrosine kinase inhibitors (EGFR-TKIs) and obtained survival benefits had somatic EGFR mutations." (PMID 33466795, 2021). "EGFR exon 20 insertions are rare genetic alterations in non-small-cell lung cancers (NSCLCs) that are usually unresponsive to approved EGFR tyrosine kinase inhibitors (TKIs)." (PMID 34680280, 2021). "Treatment planning for non-small cell lung cancer requires testing for EGFR, ALK, ROS1, BRAF, MET, RET and KRAS gene alterations." (PMID 34681592, 2021). "TNF is implicated in the secondary tumor resistance to epidermal growth factor receptor (EGFR)-blocking therapy by tyrosine-kinase inhibitors of non-small cell lung cancer." (PMID 33917839, 2021). "In non-small-cell lung cancer (NSCLC), EGFR mutation testing is used by clinicians to guide patients towards EGFR tyrosine kinase inhibitors." (PMID 34298656, 2021). "In non-small cell lung cancer (NSCLC), a “loss” of EGFR mutation has been reported under TK inhibitor therapy." (PMID 33048186, 2021). "Among these inhibitors, icotinib is a potent and selective EGFR inhibitor (IC50 = 5 nM) that was approved for the treatment of non-small cell lung cancer (NSCLC)." (PMID 34770832, 2021). "Tyrosine kinase inhibitors (TKIs) targeting the kinase domain of the epidermal growth factor receptor (EGFR), such as erlotinib, have dramatically improved clinical outcomes of patients with EGFR-driven non-small cell lung carcinomas (NSCLCs)." (PMID 34359849, 2021). "Osimertinib for instance is an epidermal growth factor receptor (EGFR) tyrosine kinase inhibitor that binds to certain mutant forms of EGFR that predominate in non-small cell lung cancer (NSCLC) tumors." (PMID 33155133, 2021). "Platinum-based chemotherapy remains the classic treatment option for patients with advanced non-small-cell lung cancer (NSCLC) who progress while receiving treatment with epidermal growth factor receptor-tyrosine kinase inhibitors (EGFR-TKIs)." (PMID 34616674, 2021). "For years the tyrosine kinase inhibitors are used in clinical studies to target the EGFR for the treatment of cancers like of non-small-cell lung cancer." (PMID 35356629, 2021). "Previous studies showed that low expression of Bim was closely related to the resistance of epidermal growth factor receptor tyrosine kinase inhibitor (EGFR-TKI) in non-small cell lung carcinomas (NSCLCs)." (PMID 34316020, 2021). "Gefitinib is a small molecule of EGFR tyrosine kinase inhibitors (TKIs) used for second- or third-line treatment of advanced non-small cell lung cancer." (PMID 33639651, 2021). "A well-known PTK associated with EGFR is Anaplastic lymphoma kinase (ALK) was identified in lymphoma, non-small cell lung cancer is the most common ALK-positive disease." (PMID 35356629, 2021). "EGFR is overexpressed in many tumors of epithelial origin, such as non-small cell lung cancer, breast cancer, glioma, head and neck cancer, cervical cancer, bladder cancer, and gastric cancer." (PMID 33658393, 2021). "EGFR-targeted therapies, including mAbs and small-molecule TKIs, have shown promising efficacy in a variety of tumor therapies, including non-small cell lung cancer, HER2-positive breast cancer, and head and neck cancer." (PMID 34879870, 2021). "A commonly used TKI is the epidermal growth factor receptor (EGFR) tyrosine kinase inhibitors (TKIs) against non-small cell lung cancer (NSCLC)." (PMID 34867402, 2021). "EGFR mutant non-small cell lung cancer patients' disease demonstrates remarkable responses to EGFR-targeted therapy, but inevitably they succumb to acquired resistance, which can be complex and difficult to treat." (PMID 34642436, 2021). "The results of this study indicate that treatment with KLT combined with EGFR-TKI is more effective than EGFR-TKI alone in the treatment for stage III/IV non-small cell lung cancer patients." (PMID 34588988, 2021).
non-small cell lung carcinoma (continued). "AURKB is a novel drug target for patients with non-small cell lung cancer with gained resistance to the therapy against EGFR." (PMID 34628367, 2021). "Genotypic and histological evolution of non-small-cell lung cancer (NSCLC) into small-cell lung cancer (SCLC) has been described as a mechanism of acquired resistance to epidermal growth factor receptor (EGFR) tyrosine kinase inhibitor (TKI) therapy." (PMID 33725888, 2021). "Despite the promising initial anti-tumor efficacy of epidermal growth factor receptor-tyrosine kinase inhibitors (EGFR-TKIs), most advanced non-small-cell lung cancers (NSCLCs) progress eventually due to therapeutic resistance." (PMID 35582379, 2021). "Studies have demonstrated that CTX treatment can promote the nuclear localization of EGFR, whereas elevated levels of nuclear EGFR were found in CTX-resistance non-small-cell lung cancer cells." (PMID 34385595, 2021). "Such adaptive mutability has also been reported for epidermal growth factor receptor (EGFR) in non-small cell lung cancers." (PMID 34208290, 2021). "In 2017, the n-hexane extract of Taiwanofungus camphoratus exhibited inhibitory activity on STAT3 pathways in EGFR wild-type NSCLC (non-small cell lung cancer) cells." (PMID 34577615, 2021). "For instance, GLI1-mediated regulation of SOX2 enhances CSC self-renewal and confers resistance to EGFR inhibitors in non-small cell lung cancer." (PMID 33958721, 2021). "In response to EGFR-TKI therapy of non-small-cell lung carcinoma (NSCLC), Notch3 physically binds to β-catenin in the cytoplasm of tumor cells to activate β-catenin signaling." (PMID 34195229, 2021). "It has been suggested that other relatively frequent mutations like EGFR and PI3KCA activations correlate with the in situ proliferation and metabolic alterations (e.g., in non-small cell lung cancer — NSCLCs and breast carcinomas)." (PMID 35029792, 2021). "We present a retrospective analysis of the impact of allelic frequency on survival in patients with EGFR mutant non-small cell lung cancer." (PMID 33869038, 2021). "In contrast, amplifications in EGFR have been found to be more prevalent in Caucasians for cancer types such as non-small cell lung cancer." (PMID 34576298, 2021). "Afatinib is approved in the European Union, USA, Canada, Switzerland, Australia, and several Asian, Latin American, and Middle Eastern countries as an oral, once-daily tablet for patients with non-small-cell lung cancer (NSCLC) and activating EGFR mutations." (PMID 33783657, 2021). "In non-small cell lung cancer (NSCLC) patients, activating mutations in the epidermal growth factor receptor (EGFR) were found to be associated with response to EGFR inhibition." (PMID 34944063, 2021). "Targeted treatment of epidermal growth factor receptor (EGFR)-mutant non-small cell lung cancer (NSCLC) is a landmark for rational therapy addressing molecular vulnerabilities." (PMID 34921211, 2021). "The EGFR/Akt signaling cascade has been identified as a crucial oncogenic regulator in various cancers, including non-small cell lung cancer(NSCLC) and prostate cancer." (PMID 34887764, 2021). "Genomic analyses of non-small cell lung cancer (NSCLC) have revealed precision medicine targets, e.g., mutated epidermal growth factor receptor (EGFR) and ALK fusions." (PMID 33671073, 2021). "We fundamentally evaluated the potency of [77Br]BrCO1686 as a molecular probe for detecting EGFR L858R/T790M using human non-small-cell lung cancer (NSCLC) cell lines: H1975 (EGFR L858R/T790M), H3255 (EGFR L858R), and H441 (wild-type EGFR)." (PMID 33809064, 2021). "Molecular targeted therapy for non-small cell lung carcinoma (NSCLC) is restricted due to resistance to epidermal growth factor receptor (EGFR) tyrosine kinase inhibitors (TKIs)." (PMID 34210314, 2021).
non-small cell lung carcinoma (continued). "Thus, the aim of this study is to estimate the proportion of positive EGFR mutations among patients diagnosed with non-small cell lung carcinoma (NSCLC) and T790M at King Khalid University Hospital (KKUH)." (PMID 34963835, 2021). "Studies have showed that the use of ICI as an adjuvant therapy in patients with drug-resistant, non-small cell lung cancer after EGFR-TKI treatment, it can make the patients increase patients’ survivals." (PMID 33633793, 2021). "Post-authorization, non-interventional Special Use Medication Program, multicenter, retrospective study in advanced EGFR/T790M+ non-small cell lung cancer." (PMID 33676426, 2021). "Tyrosine kinase inhibitors (TKI) targeting epidermal growth factor receptor (EGFR) are approved for use in metastatic non-small cell lung cancer (NSCLC)." (PMID 33892800, 2021). "Traditional Chinese medicine (TCM) with different treatment principles, in combination with EGFR-TKIs, plays an important role in the treatment of cancers including resistant non-small cell lung cancer (NSCLC)." (PMID 34646330, 2021). "It is used as a first-line treatment for patients with locally advanced or metastatic non-small cell lung carcinoma (NSCLC) with EGFR sensitizing mutations and as a treatment for patients with EGFR T790M-mutation-positive NSCLC that has progressed on or after EGFR-TKI therapy." (PMID 34834084, 2021). "For example, EGFR gene copy number has also been put forward as a candidate biomarker for predicting treatment response to EGFR inhibitors in patients with advanced non-small-cell lung cancer and colorectal cancer." (PMID 34768783, 2021). "This study to assess the real-world clinical impact of osimertinib showed high drug activity in pretreated advanced EGFR/T790M+ non-small cell lung cancer, with manageable adverse events." (PMID 33676426, 2021). "HNSCC is characterized by EGFR overexpression and amplification, while non-small cell lung cancer, especially lung adenocarcinoma, harbor frequent activating E746-A750 deletions or L858R mutations in EGFR29,30." (PMID 34725466, 2021). "Inhibitors of VEGF/VEGFR in combination with EGFR inhibitors in non-small-cell lung cancers constitute a promising strategy that targets tumor angiogenesis as well as uncontrolled growth properties of tumors." (PMID 34461089, 2021). "This is best demonstrated in non-small cell lung cancer (NSCLC), where the identification of molecular alterations in driver genes, such as EGFR mutations, led to the approval and rapid development of the small molecule tyrosine kinase inhibitors (TKIs)." (PMID 34572523, 2021). "We aimed to evaluate the effectiveness and tolerability of Afatinib as first-line treatment of advanced epidermal growth factor receptor (EGFR) mutant non small cell lung cancer (NSCLC) in a real-world setting." (PMID 34048189, 2021). "Targeting EGFR, epidermal growth factor receptor tyrosine kinase inhibitors (EGFR TKIs), brings lights to the treatment of non-small cell lung cancer (NSCLC)." (PMID 34335945, 2021). "Other authors have previously tried to predict EGFR and KRAS mutations in Non-Small Cell Lung Cancer (NSCLC) from image features." (PMID 33946756, 2021). "AURA study reported 61% objective response rate and progression-free survival of 9.6 months with osimertinib in patients with EGFR/T790M+ non-small cell lung cancer." (PMID 33676426, 2021). "The expression of EGFR receptor in CTCs has been shown to be a predictive marker for non small cell lung cancer prognosis who are undergoing second-line therapy with AXD929 (EGFR tyrosine kinase inhibitor)." (PMID 33867703, 2021). "Small-molecule tyrosine kinase inhibitors targeting oncogenic driver mutations (such as EGFR, ALK, ROS1 and BRAF) have fundamentally changed the treatment paradigm for non-small cell lung cancer (NSCLC)." (PMID 34037224, 2021).
non-small cell lung carcinoma (continued). "The tyrosine kinase inhibitors (TKIs) targeting epidermal growth factor receptor (EGFR) have been widely used for non-small cell lung cancer (NSCLC) patients, but the development of acquired resistance remains a therapeutic hurdle." (PMID 34155348, 2021). "The EGFR signaling pathway was enhanced and induced proliferation and metastasis of non-small cell lung cancer cells." (PMID 34168980, 2021). "The ADJUVANT study reported the comparative superiority of adjuvant gefitinib over chemotherapy in disease-free survival of resected EGFR-mutant stage II–IIIA non-small cell lung cancer (NSCLC)." (PMID 34750392, 2021). "Aberrant signaling of EGFR due to overexpression or somatic mutations—amino acid replacements, deletions or insertions—has suggested a role for EGFR in many types of human cancers, the most common cancer being non-small cell lung cancer (NSCLC)." (PMID 33807850, 2021). "Gefitinib, which is selective for the epidermal growth factor receptor (EGFR), was developed as an oral cancer treatment directed against non-small cell lung cancer (NSCLC), and is effective in patients with specific mutations of EGFR." (PMID 34208076, 2021). "used different radiomic features, feature selection and classifiers of multimodal images to construct prediction models and observed their performance in predicting the mutation status of EGFR and KRAS in non-small cell lung cancer." (PMID 33596844, 2021). "This trial will utilize genomic, proteomic, epigenomic, and metabolomic data to determine the different mechanisms underlying treatment efficacy and the development of resistance to afatinib of non-small cell lung cancer patients expressing EGFR." (PMID 33855679, 2021). "For example, PCR-based ctDNA assays for EGFR genotyping in non-small cell lung cancer, and for KRAS genotyping in colorectal cancer have demonstrated clinical validity and thus have received regulatory approval in the United States and Europe." (PMID 34194620, 2021). "The activation of EGFR can upregulate the expression of PD-L1 in non-small-cell lung cancer (NSCLC)." (PMID 34805266, 2021). "In non-small cell lung cancer (NSCLC), identifying the presence of sensitizing and resistance epidermal growth factor receptor (EGFR) mutations dictates treatment plans." (PMID 34692681, 2021). "We report a case of a 64-year-old male with stage IV adeno-non-small cell lung cancer (NSCLC) harboring an exon 19 deletion in the epidermal growth factor receptor (EGFR) treated with osimertinib 80 mg/d for first-line targeted therapy." (PMID 34802213, 2021). "Epidermal growth factor receptor (EGFR) -tyrosine kinase inhibitors (TKIs) have revolutionized the treatment of patients with EGFR-mutant non-small cell lung cancer (NSCLC)." (PMID 34397927, 2021). "The later generation TKI’s have seen some success in treating these resistant cases, and targeted sequencing of the EGFR locus has become a common practice in treatment of non-small cell lung cancer." (PMID 33968733, 2021). "Although the efficacy of epidermal growth factor receptor-tyrosine kinase inhibitor (EGFR- TKI) therapy has been proven in non-small cell lung cancer (NSCLC) patients, acquired resistance to EGFR-TKIs presents a serious clinical problem." (PMID 34367462, 2021). "Epidermal growth factor receptor-tyrosine kinase inhibitors (EGFR-TKIs) have elicited favorable anti-tumor activity in non-small cell lung cancer especially the lung adenocarcinoma." (PMID 33546082, 2021). "Antitumor activity and the efficacy of alleviating diarrhea are the pharmacological basis of combining TCMs with EGFR-TKI in the treatment of non-small-cell lung cancer." (PMID 33868436, 2021). "The first-generation EGFR tyrosine kinase inhibitors represented a breakthrough for a subset of patients with non-small cell lung cancer." (PMID 33777559, 2021).